BRCA1 (BRCA1 DNA repair associated)
Diseases named in the same sentence as BRCA1 in open-access papers (continued):
Sharing a sentence is not in itself a finding about the gene and the disease.
prostate adenocarcinoma (8 papers, 2017 to 2025). "Here, we report a patient in whom serial cell-free DNA (cfDNA) monitoring for his known prostate adenocarcinoma uncovered the emergence of an unexpected FGFR3-TACC3 gene fusion, a BRCA1 frameshift mutation, and other molecular abnormalities." (PMID 37980380, 2023).
basal cell carcinoma (7 papers, 2008 to 2024). A carcinoma involving the basal cells. "In an earlier study of this cohort, we reported an excess risk of basal cell carcinoma in BRCA1 and BRCA2 carriers." (PMID 38741145, 2024). "Those upregulated in tumors with germline BRCA1 mutation were related to endothelial-to-mesenchymal transition (EMT) in basal cell carcinoma." (PMID 32719318, 2020). "Interestingly, one of the BRCA1-floxed male mice developed spontaneous basal cell carcinoma (BCC) of the skin." (PMID 28869585, 2017).
bone cancer (7 papers, 2012 to 2024). A primary or metastatic malignant neoplasm affecting the bone or articular cartilage. "Anti-RANKL mAB therapy shows potential in BRCA1-mutational driven BC and is approved for some types of bone cancer." (PMID 38715609, 2024). "By implementing the analysis modes provided by the Correlation AnalyzeR database application, we uncovered novel insights about BRCA1′s role in bone cancer, particularly with respect to the NRF2 pathway." (PMID 33879054, 2021). "However, BRCA1 and BRCA2 mutations can increase bone cancer incidence based on one and two studies, respectively." (PMID 34577828, 2021). "Furthermore, our analysis led to the identification of NRF2 pathway members which might be involved in mediating bone cancer progression in response to changes in BRCA1 activity." (PMID 33879054, 2021).
brain cancer (7 papers, 2010 to 2025). A primary or metastatic malignant neoplasm affecting the brain. "One (2%) man with a BRCA1 pathogenic mutation was diagnosed with brain cancer (oligoastrocytoma) (Part B in S2 Fig)." (PMID 30040829, 2018). "Searching BRCA1 in PubMeth returned 7 related types of cancer, namely, breast, ovarian, lung, gastric, cervical, pancreatic, and brain cancer." (PMID 22168213, 2011). "The brain cancer case also had a P/LPGV in BRCA1, which is also a discordant phenotype." (PMID 41465149, 2025). "Also, understanding the role of BRCA1 in initiation of brain cancer is important as its role is less well understood in brain cancer." (PMID 35370679, 2022). "No relatives of known BRCA1 or BRCA2 carriers were diagnosed with brain cancer." (PMID 20877337, 2010).
cervical squamous cell carcinoma (7 papers, 2014 to 2025). A squamous cell carcinoma arising from the cervical epithelium. "A previous study of cervical squamous cell carcinoma (CSCC) suggested that BRCA1 overexpression may have been associated with resistance to concurrent chemoradiotherapy (CCRT) in a subset of patients." (PMID 40732337, 2025). "BRCA1 enhanced the sensitivity of cervical squamous cell carcinoma (CSCC) patients to cisplatin-based CCRT by up-regulating STAT1 to activate the JAK/STAT pathway." (PMID 35409328, 2022). "Therefore, our findings demonstrate that baseline FANCD2, RAD51, BRCA1 and BRIP1 nuclear protein expression could have an important role in treatment failure in advanced squamous cervical cancer." (PMID 24708616, 2014).
childhood cancers (7 papers, 2014 to 2023). "FA caused by BRCA1/2 PGVs is strongly associated with distinct spectra of embryonal childhood cancers, AML with BRCA2-PGVs and early epithelial cancers with BRCA1 PGVs." (PMID 36551764, 2022). "In turn, recent large genetic studies of individuals affected by apparently sporadic childhood cancer detected BRCA1/2 variants, which point also towards a possible role for germline PGVs in particular of BRCA2 in the development of some non-syndromic childhood cancers." (PMID 34680915, 2021). "Bi-allelic BRCA1 mutations are likely to be lethal at the embryonic stage, while such mutations in BRCA2 lead to Fanconi anemia type D1, with increased risk of childhood cancer." (PMID 35356428, 2022). "Two large scale studies identified germline BRCA2 PGVs in a small number (13/2081 total across both studies) of childhood cancers and just one germline BRCA1 PGV." (PMID 34680915, 2021). "In the St Jude’s cohort of long-term survivors of childhood cancer germline BRCA1/2 PGVs were detected in 34 (BRCA2 n = 20, BRCA1 n = 14)/4402 individuals." (PMID 34680915, 2021). "However, increasing studies are indicating the presence of germline BRCA1 in both malignant and benign childhood cancers." (PMID 37736432, 2023). "Initial studies investigating a potential role of germline BRCA1 and BRCA2 PGVs also for predisposition for non-syndromic childhood cancer focussed on the incidence of childhood cancers in the offspring of families presenting with HBOC, in which a germline BRCA1/2 PGV had been detected." (PMID 34680915, 2021). "Here we review aspects of the clinical, genetic, and biological role of BRCA1 and BRCA2 in the context of FA and childhood cancer and discuss clinical and biological implications." (PMID 34680915, 2021). "When compared with non-BRCA1/2 HBOC families no excess of childhood cancer was demonstrated in the families with a germline BRCA1/2 PGV." (PMID 34680915, 2021).
chronic myeloid leukemia (7 papers, 2006 to 2022). "BRCA1 mutations are detected in AML patients (although at a low frequency), and BRCA1 expression is decreased in chronic myelogenous leukemia (CML) cells." (PMID 36346676, 2022). "TIAR is also a negative regulator of the BRCA1 oncogene; it has been shown to block translation and reduce the protein expression of BRCA1 in chronic myeloid leukemia cells, which leads to aneuploidy, spindle toxin resistance and genomic instability." (PMID 35887183, 2022). "TIAL1 is a negative regulator of BRCA1: it is shown to block translation, and at least in chronic myeloid leukemia cells, reduce the protein expression of BRCA1 which leads to aneuploidy, spindle toxin resistance, and genomic instability." (PMID 32714364, 2020). "In chronic myeloid leukaemia, it has been shown that expression of the p210 BCR-ABL fusion protein leads to a downregulation of BRCA1 protein expression, owing to post-transcriptional mechanisms." (PMID 17047656, 2006).
cutaneous melanoma (7 papers, 2018 to 2026). A primary melanoma arising from atypical melanocytes in the skin. "However, in terms of pathogenicity, only a few BRCA1/2 mutations in cutaneous melanoma (8/48, 16.7%) and tumors located in the head and neck (5/27, 18.5%) and CNS (1/7, 12.5%) were deleterious." (PMID 33054725, 2020). "A pan-cancer analysis done on 33 cancers including cutaneous melanoma and uveal melanoma observed significantly higher HRDsum scores calculated based on LOH, LST, and TAI in patients with 22 different HRR mutations including BRCA1 and BRCA2." (PMID 41533995, 2026). "In cutaneous melanoma, mutations in BRCA1/2 were not statistically different between LOH-high and LOH-low (BRCA1: 1.30% v 1.12%, P = .705; BRCA2: 0.65% v 2.07%, P = .358)." (PMID 41533995, 2026). "She had three children: a 53-year-old son (III.4), who had received a diagnosis of cutaneous melanoma two years before, but with no mutations; a 51-year-old daughter (III.5) carrying no mutations; and an asymptomatic 48-year-old daughter (III.6) positive to the mutation of the BRCA1 gene." (PMID 29346284, 2018).
Insulin resistance (7 papers, 2012 to 2026). Increased resistance towards insulin, that is, diminished effectiveness of insulin in reducing blood glucose levels. "Interestingly, BRCA1/2 mutation carriers often have very low or very high levels of insulin-like growth factor 1 (IGF-1) in the serum compared to non-carriers, which is associated with an increased risk for insulin resistance." (PMID 39621070, 2025).
kidney cancer (7 papers, 2012 to 2023). Primary or metastatic malignant neoplasm involving the kidney. "Among 688 unselected kidney cancer cases a BRCA1 mutations was reported in three patients (0.4%) (OR = 1.0; 95% CI 0.29–3.51; p = 1.0)." (PMID 35395863, 2022). "In total, 688 kidney cancer cases were genotyped for BRCA1 mutations (5328 insC, C61G, 4153 delA)." (PMID 35395863, 2022). "Our goal was to determine the prevalence of specific founder mutations genes BRCA1 (5328 insC, C61G and 4153 delA) and BRCA2 (C5972T) mutations in bladder and kidney cancer patients from Poland." (PMID 35395863, 2022). "During follow-up period, a stage I kidney cancer was discovered incidentally with ultrasound in a 47-year-old BRCA1 carrier and later she was successfully operated on." (PMID 35938029, 2022). "However, a recent large (with almost 15,000 BRCA1/2 PV carriers) analysis did not detect any significant association between kidney cancer and BRCA1/2 variants leaving little room for our data from small numbers of cases and controls to claim the opposite." (PMID 35938029, 2022). "The mutations BRCA1 and BRCA2 seem not to play a role in bladder and kidney cancer development in Polish patients." (PMID 35395863, 2022). "In conclusion, this study reveals that mutations in BRCA1 gene (5328 insC, C61G, 4153 delA) and mutation (C5972T) of gene BRCA2 did not seem to play a major role in bladder or kidney cancer development." (PMID 35395863, 2022).
meningioma (7 papers, 2007 to 2025). A generally slow growing tumor attached to the dura mater. "CREBBP, PIK3CA (R108H), PIK3R1, BRCA1, and SMARCB1 are the most represented mutations; unfortunately, none of these mutations can predict the rate of recurrence in NF2-mutated meningiomas." (PMID 35892898, 2022). "Other common driver mutations in our cohort such as CDKN2A, ARID1A, BRCA1, NF1, AKT1, SMO, PIK3CA have similarly been noted in various prior sequencing studies of meningiomas." (PMID 31191822, 2019). "TMEM97 was first identified as a downregulated gene in meningioma and was later found to be transcriptional target of the BRCA1 gene." (PMID 18070364, 2007). "CDKN2A, ARID1A, BRCA1, NF1, and AKT1 were also commonly identified in meningioma samples across the cohort." (PMID 31191822, 2019). "Interestingly, a 50 years old male patient with parasagittal meningioma and pathologically diagnosed as RDD (Patient No.5) harbored a pathogenic mutation in BRCA1 (c.2157dupA)." (PMID 40406258, 2025).
mucinous ovarian cancer (7 papers, 2012 to 2024). An invasive malignant neoplasm that arises from the ovary and is characterized by the presence of malignant epithelial cells that contain intracytoplasmic mucin and may resemble the epithelial cells of the endocervix or gastrointestinal tract. "Of note, we reported already the finding of deleterious BRCA1/2 variants in patients with clear cell and mucinous ovarian cancer within an international multicenter first line therapy trial." (PMID 29053726, 2017). "As BRCA1/2 status affects clinical management of affected women, current guidelines recommend BRCA1/2 testing in all non-mucinous ovarian cancer cases." (PMID 33086730, 2020). "Consequently, the current guidelines recommend BRCA1/2 testing in all non-mucinous ovarian cancer cases." (PMID 33086730, 2020). "Previous studies have shown that mucinous ovarian carcinomas did not carry BRCA1/2 mutations." (PMID 32856862, 2020). "On the other hand, mucinous ovarian cancer is not found to be associated with BRCA1/2 genes." (PMID 22234272, 2012).
rectal cancer (7 papers, 2017 to 2023). A primary or metastatic malignant neoplasm that affects the rectum. "Through Spearman correlation analysis, the association of BRCA1, CLU, AGTR1, and KL expression with the CNA value was estimated across rectal cancer." (PMID 35083278, 2021). "This study also evaluated the correlation of BRCA1, CLU, AGTR1, and KL expression with methylation levels in rectal cancer." (PMID 35083278, 2021). "Through the cBioPortal tool, we evaluated CNAs of BRCA1, CLU, AGTR1, and KL across rectal cancer." (PMID 35083278, 2021). "Besides, Some of the included studies did not distinguish between BRCA1 and BRCA2, and some did not distinguish between colon and rectal cancer." (PMID 37644384, 2023).
Type 2 Diabetes (7 papers, 2013 to 2025). "Women with BRCA1/2 mutations more frequently develop type-2 diabetes after a BC diagnosis compared with carriers without cancer." (PMID 34869002, 2021).
uveal melanoma (7 papers, 2015 to 2026). A melanoma derived from melanocytes of the uveal tract. "There was incident case of uveal melanoma in a 49 year old women with a BRCA1 mutation in our study who was not included in the analysis." (PMID 38741145, 2024). "Inactivation of the BAP1 gene which codes for an enzyme that binds to BRCA1 and BARD1 in regulating the tumor suppressor complex has been described in up to 84% of class 2 uveal melanomas." (PMID 25874144, 2015).
bone marrow failure (6 papers, 2015 to 2025). "Notably, biallelic mutations in certain FA pathway genes, such as FANCS/BRCA1, FANCO/RAD51C, FANCR/RAD51, and FANCM can cause an FA-like disorder that shares the cancer predisposition of classical FA and, in some cases, the associated developmental abnormalities, but lacks bone marrow failure." (PMID 41155398, 2025).
cardiomyopathy (6 papers, 2018 to 2023). A disease of the heart muscle or myocardium proper. "It will be of interest to determine whether Brca1 deletion alleviates the cardiomyopathy-related phenotypes associated with Cobra1 gene disruption." (PMID 29426838, 2018). "Taken together, these results suggest overtreatment of HR-positive, HER2-negative disease in BRCA1 and 2 PV carriers, which may expose patients unnecessarily to toxicities including neuropathy (platinums), cardiomyopathy, and secondary hematologic malignancies (anthracyclines)." (PMID 35723570, 2022).
dementia (6 papers, 2013 to 2025). Loss of intellectual abilities interfering with an individual's social and occupational functions. "BRCA1, a key tumor suppressor, has been linked to both dementia and neuronal cell death." (PMID 39902325, 2025). "A study reported that stroke was associated with cognitive impairment and dementia in older adults, and the six RNA-binding protein (RBP) genes (POLR2F, DYNC1H1, SMAD9, TRIM21, BRCA1, and ERI1) might participate in the process by mediating the hypoxic responses and angiogenesis." (PMID 37006557, 2023).
ovarian adenocarcinoma (6 papers, 2014 to 2025). An adenocarcinoma that arises from the ovary. "PARP inhibition therapy has shown significant therapeutic success in patients diagnosed with advanced ovarian adenocarcinomas with germline BRCA1/2 mutations." (PMID 31850215, 2019). "The BRCA1/BRIP1 GDH patient is a 46-year-old female diagnosed with advanced ovarian adenocarcinoma at clinical stage FIGO IVB, exhibited severe chemotherapy-induced toxicity and postoperative complications, including chylous leakage." (PMID 40777133, 2025). "DNA sequencing of 172 human tissue samples of advanced-stage ovarian adenocarcinoma identified 36 samples with a clinically significant tier 1/2 sequence variants (point mutations and in/dels) and 9 samples with a CNV causing a loss of function in BRCA1/2." (PMID 32483276, 2020).
ovarian serous cystadenocarcinoma (6 papers, 2017 to 2025). A malignant serous cystic epithelial neoplasm arising from the ovary. "Two cases of ovarian serous cystadenocarcinoma with no history of family tumors were normalized for BRCA1/2 gene sequencing." (PMID 32356124, 2020).
adenoma (5 papers, 2017 to 2024). A neoplasm arising from the epithelium. "In this study, the results of qPCR indicated that the highest levels of BRCA1 are presented in a complex carcinoma (CCa1), while cultured cells obtained from a complex adenoma showed the highest levels of BRCA2, followed by complex carcinomas." (PMID 28945747, 2017).
Bloom syndrome (5 papers, 2014 to 2022). Bloom syndrome (BSyn) is a rare chromosomal breakage syndrome characterized by a marked genetic instability associated with pre- and postnatal growth retardation, facial sun-sensitive telangiectatic erythema, increased susceptibility to infections, and predisposition to cancer. "The mechanisms underlying ALT are unclear but involve several proteins involved in homologous recombination including the BLM helicase, mutated in Bloom's syndrome, and the BRCA1 tumor suppressor." (PMID 25084169, 2014). "Furthermore, the spontaneous HR frequency for Brca2 delta 11 conditional heterozygotes in this study is similar to that of earlier studies from our laboratory including Blm (the genes associated with Bloom’s syndrome) and Brca1 conditional heterozygote samples." (PMID 34359565, 2021).
clear cell ovarian cancer (5 papers, 2018 to 2024). "The histopathologic diagnosis was clear-cell ovarian carcinoma (pTNM: pT3a, Nx); analysis of the BRCA1 and 2 mutation was negative." (PMID 36233471, 2022). "Herein we present the provincial statistics on uptake of index BRCA1 and BRCA2 genetic testing in BC before and after the 2010 campaign comparing rates of testing between serous cancer patients and endometrioid and clear cell ovarian cancer patients." (PMID 29506471, 2018).
cognitive deficits (5 papers, 2015 to 2024). "Our study shows that BRCA1 critically contributes to DSB repair in central neurons and that neuronal reductions in BRCA1 cause increased persistence of DSBs, abnormal chromatin remodelling, cellular dysfunction and cognitive deficits." (PMID 26615780, 2015). "In this regard, in an AD model, brain of mice with knockdown of BRCA1 exhibited increased DSBs with learning and cognitive deficits." (PMID 39683594, 2024). "In AD brains a depletion of BRCA1, likely due to Aβ1-42, enhanced the cognitive deficits." (PMID 34073287, 2021). "To determine whether BRCA1 is altered in humans with AD, we immunostained post-mortem brain sections from people who had no cognitive deficits and a Braak score of 0 (controls) and from patients with mild cognitive impairment (MCI) or AD with an antibody against BRCA1." (PMID 26615780, 2015). "In addition, downregulations in BRCA1 have been reported in hippocampal neurons of mild cognitive impairment (MCI) and AD brains, suggesting that BRCA1 plays an essential role in AD." (PMID 39683594, 2024).
COVID-19 (5 papers, 2021 to 2023). A disease caused by infection with severe acute respiratory syndrome coronavirus 2. "This study aims to evaluate the outcomes of COVID-19 vaccination among germline PV/LPV carriers in BRCA1/2." (PMID 37046302, 2023). "We conducted a phone call survey of COVID-19 vaccination uptake and toxicity in a prospective cohort of 189 participants with germline BRCA1/2 PV/LPV between 1st Sept 2021 and 30th Sept 2021." (PMID 37046302, 2023). "This study evaluated the safety profile of COVID-19 vaccination on a cohort of individuals with germline PV/LPV in BRCA1/2 and showed that the post-vaccination side effects profile experienced were similar with the general population with no major side effects." (PMID 37046302, 2023). "As such recommendations with regards to COVID-19 vaccination for eligible individuals with germline PV/LPV in BRCA1/2 should not differ from non-carriers and should be encouraged by their healthcare providers." (PMID 37046302, 2023).
developmental delay (5 papers, 2015 to 2019). "Also the two cases with biallelic BRCA1 mutations were found to be associated with developmental delay, while for one of the patients, mental retardation was mentioned explicitly." (PMID 26681308, 2015).